LEP (leptin)
Diseases named in the same sentence as LEP in open-access papers (continued):
Sharing a sentence is not in itself a finding about the gene and the disease.
endometrial cancer (continued). "The results showed that cisplatin reduces the transcriptional activity of selected genes, while leptin promoted the expression of mRNA JAK2 and STAT3 in endometrial cancer cells (p < 0.05)." (PMID 32531934, 2020). "The obtained results showed that leptin siRNA inhibited the expression of JAK2 and STAT3 proteins both in the Ishikawa culture untreated with cisplatin (0 h) and the endometrial cancer culture incubated with cisplatin for 12, 24 and 48 h." (PMID 32531934, 2020). "Remarkably, leptin treatment stimulated the proliferation and invasion of SPEC-2 cells (type-II endometrial cancer cell line)." (PMID 30510663, 2018). "The analysis of endometrial cancer (EmCa) biopsies showed that NILCO (Notch1–4, ligands, IL-1/IL-1R, leptin and Ob-R) molecules were expressed higher in type II EmCa." (PMID 30004402, 2018). "In the present study, in endometrial cancer cells and normal HEEs, a decrease of LSR induced by leptin and an increase of LSR induced by adiponectin were observed." (PMID 27036040, 2016). "In leptin-treated human chondrosarcoma, hepatocellular and endometrial carcinoma cells AKT phosphorylation was found to be increased, and inhibition of PI3K with specific inhibitors abolished leptin-induced proliferation, migration and invasion." (PMID 20030801, 2009). "ADIPOR1 was significantly lower in patients without LVSI (p = 0.007), and leptin was significantly higher in patients with grade 2 endometrial cancer than grade 1 (p = 0.045)." (PMID 40642843, 2025). "Leptin levels were higher in endometrial cancer tissue compared to control endometrium, but unlike adiponectin, leptin levels in plasma were also elevated in the cancer patients." (PMID 40642843, 2025). "The increased mRNA expression of adiponectin (ADIPOQ), leptin, IL6, and TNFα in endometrial cancer tissue highlights an enhanced inflammatory and metabolic state within the tumor microenvironment, which may drive cancer progression." (PMID 40642843, 2025). "On univariate analysis, leptin levels showed significantly higher values in type 1 endometrial cancer compared to type 2 (p = 0.035) and in patients without MELF (p = 0.022)." (PMID 38339282, 2024). "Leptin and IGF 1 and 2 were not linked to endometrial cancer risk, except for IGF1 and 2 increasing the risk of type 1 endometrial cancer in obese individuals (p = 0.005 and 0.004, respectively)." (PMID 38339282, 2024). "Among type II endometrial cancer patients, BMI and leptin did not correlate with any of the prognostic parameters, whereas there was a positive correlation between IL-6 and the presence of distant metastases." (PMID 35053431, 2022). "We found that BMI, leptin, IL-6, and reactive oxygen species correlated with T, N, and M status in type I, but not in type II endometrial cancers." (PMID 35053431, 2022). "Among the type II endometrial cancer patients, BMI and leptin did not correlate with any of the prognostic parameters, whereas a positive correlation between IL-6 and M status/stage was found." (PMID 35053431, 2022). "In the type II endometrial cancer patients, we did not observe any correlations between oxidative stress markers, BMI, or leptin, while we demonstrated a significant linear relationship between ROS and IL-6." (PMID 35053431, 2022). "Based on the obtained results, changes in the level of the expression of leptin can be noticed, but in the culture not exposed to cisplatin, its level is higher than in the case of endometrial cancer cells incubated with the drug." (PMID 32531934, 2020). "Unlike the situation in endometrial carcinoma, the circulating levels of leptin in patients with ovarian malignancies generally have been shown to be lower in comparison with healthy or non-cancer controls." (PMID 30510663, 2018). "In addition, in endometrial cancer cells, downregulation of LSR by leptin via PI3K and JAK2/STAT and upregulation of LSR by adiponectin via MAPK and JAK2/STAT were observed." (PMID 27036040, 2016).
endometrial cancer (continued). "Conversely, leptin only induced IL-1R tI in human endometrial cancer cells, An3Ca, SK-UT2 and Ishikawa cells, compared to non-malignant cells, HES and primary human endometrial cells, through a mechanism involving JAK2, PI-3K and MAPK/mTOR signaling pathways." (PMID 24202338, 2013). "Leptin pro-angiogenic effects seem to be common in cancer since leptin differentially induces VEGF/VEGFR-2 in endometrial cancer, but not in normal cells." (PMID 21731759, 2011). "The aim of the present study was to prospectively evaluate the association of established tumor prognostic factors with BMI and blood levels of leptin, proinflammatory cytokines, and oxidative stress markers among patients with type I endometrioid and type II non-endometrioid endometrial cancers." (PMID 35053431, 2022). "However, the role of leptin in the maintenance stem cell of endometrial cancer has not been determined to date and requires further study." (PMID 31440472, 2019). "The balance of leptin and adiponectin levels in individuals, rather than leptin or adiponectin levels alone, may indicate such physiological changes as the development of endometrial cancer." (PMID 24944677, 2014). "Although, all the mechanism(s) by which leptin contributes to tumour progression are unknown, our published data suggest that specific leptin signalling increase cancer-cell proliferation and the expression of VEGF/VEGFR2 in breast and endometrial cancer, and in endometriotic lesions." (PMID 21139583, 2011). "In our study, we observed significantly higher levels of leptin and FGF21, but not of FGF23, in overweight and obese patients with endometrial cancer." (PMID 32570721, 2020). "In our studies, a strong correlation was observed between the FGF23 and leptin hormone levels, while no statistically significant increase in the levels of FGF23 was observed in obese patients with endometrial cancer." (PMID 32570721, 2020). "This study examined a set of six markers, namely, adiponectin, leptin, IL6, TNFα, IGF1, and IGF2 and compared them between fifty age-matched endometrial cancer patients (study group) and non-cancer patients with benign gynaecological conditions (control group)." (PMID 38339282, 2024).
COVID-19 (78 papers, 2020 to 2026). A disease caused by infection with severe acute respiratory syndrome coronavirus 2. "Although just above the p-value threshold and given the very close replicated estimate, we consider the association between leptin and COVID-19 severity as confirmed (OR = 1.222; 95% CI: 1.021−1.424, p = 5.08 × 10−2)." (PMID 41359762, 2025). "Mediation analysis was performed for leptin as it showed evidence of positive association with both BMI and COVID-19." (PMID 41359762, 2025). "The potential causal effect of BMI on leptin and leptin on COVID-19 severity were replicated and confirmed using different independent GWAS dataset." (PMID 41359762, 2025). "The difference in leptin, adiponectin, and resistin gene/protein expression in abdominal visceral or subcutaneous adipose tissue and their relationship with long COVID-19 symptoms risk merits be discussed." (PMID 39469144, 2024). "Of note, lower adiponectin-to-leptin ratio, a surrogate of adipocyte function, showed an association with worse COVID-19 outcomes." (PMID 37934800, 2024). "Collectively, our data imply that the commencement of COVID-19 is linked with alterations in visfatin levels, while changes in leptin remain inconclusive." (PMID 39200926, 2024). "Mainly, PAL was associated with changes in IL-10, triglyceride, and leptin levels in the plasma of post-COVID-19 patients." (PMID 37753077, 2023). "The results showed that decreases in the adiponectin/leptin ratio were significantly associated with AT dysfunction and COVID-19-related pneumonia onset in COVID-19 patients." (PMID 37408184, 2023). "The aim of this study was to examine the association between levels of circulating leptin and adiponectin and the severity and mortality of COVID-19." (PMID 36960389, 2023). "Yet, in a cohort of 31 COVID-19 patients from China, leptin levels predicted disease severity and were associated with disease progression." (PMID 37238973, 2023). "Previous studies showed that leptin was associated with greater monocyte proliferation and activation in COVID-19 cases." (PMID 37217748, 2023). "Mechanistically, leptin levels have been associated with the immunologic aberrations and systemic pro-inflammatory state that typically occur in COVID-19 patients." (PMID 37686837, 2023). "Many studies exist on the association between leptin and monocytes in children, whereas the association between leptin and monocytes was observed in adult COVID-19 patients." (PMID 35736018, 2022). "Leptin has been linked with airway reactivity, and current research indicates that leptin concentrations are increased in COVID-19 cases with significant pulmonary inflammation." (PMID 34777870, 2021). "We sought therefore, to examine in COVID-19 patients with different severity of the disease, the adiponectin/leptin ratio as a predictor of outcome and the association of these hormones with BDNF concentration in the circulation." (PMID 34957187, 2021). "Leptin was associated with both BMI and COVID-19 severity, and we also tested its mediation effect." (PMID 41359762, 2025). "Visceral adipose tissue is more metabolically active than subcutaneous adipose tissue and secretes a variety of adipokines and pro-inflammatory cytokines, including interleukin 6 (IL-6) leptin, which is associated with the severity of pulmonary inflammation in COVID-19 patients." (PMID 39311212, 2024). "DKK-1 also induces the formation of adipocytes; therefore, its lower levels in placenta could also be linked with the lower leptin levels recorded in mothers who suffered COVID-19 in the current study." (PMID 38610889, 2024). "Indeed, although still not conclusive, adiponectin levels have been found to be significantly lower in patients with COVID-19, while higher leptin levels have been linked to the cytokine storm during the infection." (PMID 36674646, 2023).
COVID-19 (continued). "Serum levels of leptin and adiponectin were determined at admission in 123 individuals with confirmed COVID-19 and their association with 90-day mortality and respiratory failure was analyzed by logistic regression analysis and expressed as odds ratios (ORs) with 95% confidence intervals (CIs)." (PMID 36960389, 2023). "In adults, adipocyte deregulation associated with leptin might be promoting the progression of ARDS in COVID-19 patients." (PMID 37013538, 2023). "Notably, leptin levels have been associated with the immunologic abnormalities and systemic pro-inflammatory state seen in COVID-19 patients." (PMID 36674646, 2023). "Intact LEP signalling is needed for a normal regulatory T-cell response, which has also been suggested to be one of the immunological linked to disturbances involved in the pathogenesis of the cytokine storm seen in patients with COVID-19." (PMID 33512658, 2021). "The dysregulation of leptin in COVID-19 patients could be linked to IL-6 cytokine signaling because it shares the IL-6 receptors." (PMID 34220807, 2021). "Adipocyte dysfunction linked to leptin could be contributing to the expansion of ARDS in COVID-19 patients." (PMID 34220807, 2021). "However, high circulating leptin levels have been hypothesized to be linked to the expansion of the cytokine storm related to COVID-19 aggravation, acute respiratory distress syndrome, and multiple organ failure, especially in obese patients." (PMID 36674646, 2023). "The adiponectin and leptin serum levels were only evaluated upon patients’ admission, which did not allow the researchers to draw conclusions based on the causal correlations between the adiponectin/leptin ratio and the possible clinical outcomes in the studied COVID-19 sample." (PMID 37408184, 2023). "Thus, we decided to evaluate whether leptin is increased in patients with COVID-19 and associated with basic clinical variables on mortality and morbidity." (PMID 35052684, 2021). "Our study confirmed the statistically significant effect of high BMI levels on leptin and added to the evidence linking it to worsening COVID-19." (PMID 41359762, 2025). "Our study aims to examine the changes in serum concentrations of pro-inflammatory adipokines—visfatin and leptin—in COVID-19 patients in relation to a healthy control group." (PMID 39200926, 2024). "While there are no reports of vaccine induced serum Leptin increases, there are reports of elevated plasma Leptin in intensive care patients with COVID-19 compared to healthy study participants." (PMID 39931577, 2024). "On the other hand, GLP-1 and leptin were lower (p < 0.05 and p < 0.001, respectively) in the COVID-19 group compared with the control group." (PMID 38610889, 2024). "In patients with severe and critical COVID-19, D-dimer, and IL-8 were correlated with age, while leptin levels were positively correlated with BMI and sex, indicating increased levels in males." (PMID 39507250, 2024). "The study found a decrease in the median levels of leptin from leptin 1 to leptin 2 in COVID-19 patients by −1530.5 pg/mL (Q1–Q3: −12,121.3; 3524.03) with a p-value of 0.076." (PMID 39200926, 2024). "The correlation between plasma leptin levels and COVID-19 severity has been previously investigated, but the findings have been inconsistent." (PMID 39200926, 2024). "Elevated leptin levels have been identified in both mild and severe cases of COVID-19, and its prognostic capability has surpassed even that of traditional inflammation markers like IL-6 and CXCL-101." (PMID 39062978, 2024). "The serum levels of visfatin and leptin in COVID-19 patients have been found to be significantly higher than in healthy control groups." (PMID 39200926, 2024). "Some studies reported elevated leptin levels in COVID-19 patients in the ICU, while others found a decrease in leptin levels in severe cases compared to mild and moderate ones." (PMID 39200926, 2024).
COVID-19 (continued). "Other noteworthy sex-specific correlations observed in severe COVID-19 patients are leptin, which is correlated with BMI, while TNF-R1 is correlated with age in both severe males and females." (PMID 39507250, 2024). "Our analysis aimed to assess the changes in visfatin and leptin serum concentrations among COVID-19 patients upon admission and on the seventh day of the disease (t2) compared to a healthy control group." (PMID 39200926, 2024). "Regarding leptin, it is worth mentioning that the “satiety hormone” has previously been reported to be elevated in both plasma and adipose tissue of COVID-19 patients." (PMID 38396763, 2024). "Recent investigations into the biological determinants of severe COVID-19 manifestations have spotlighted leptin, a plasma protein, as a significant factor." (PMID 39062978, 2024). "Yet a decrease in Leptin in severe COVID-19 patients compared to mild and moderate COVID-19 was also found." (PMID 36509969, 2023). "On the other hand, acute COVID-19 children exhibited higher levels of Adipsin and Leptin in comparison to convalescent and control children." (PMID 37013538, 2023). "Several other studies also reported higher serum leptin levels in COVID-19 patients compared to healthy controls." (PMID 37238973, 2023). "In WAT of COVID-19 cases, it is of interest to note that leptin transcription was upregulated independently of the presence of virus in the tissue." (PMID 37246981, 2023). "Acute COVID-19 children had significantly elevated levels of adipsin, leptin, insulin, C-peptide, glucagon and ghrelin in comparison to convalescent COVID-19 and controls." (PMID 37013538, 2023). "Of note, leptin levels were increased in patients with COVID-19 compared with the controls as well as in severe patients with COVID-19 compared with mild patients." (PMID 37240656, 2023). "In our study, we found that the leptin levels in the cohort of COVID-19 patients were higher than in controls and were possibly predictors of COVID-19, as demonstrated by the ROC curve analysis." (PMID 36674646, 2023). "Recent studies identified that plasma leptin was increased in COVID-19 patients admitted to the ICU, whereas a decrease in Leptin in severe COVID-19 patients compared to mild and moderate COVID-19 has also been reported." (PMID 36509969, 2023). "As a result, the reduction in leptin was observed only in critical COVID-19 patients admitted to the ICU during the first COVID-19 wave (without dexamethasone)." (PMID 36509969, 2023). "In severe COVID-19 patients, IL-6 levels positively correlated with the levels of Adiponectin, Visfatin, Resistin and negatively correlated with plasma leptin levels." (PMID 36509969, 2023). "The results showed that leptin levels were significantly higher in the studied COVID-19 patients than in the controls." (PMID 37408184, 2023). "The leptin levels were significantly higher in COVID-19 patients than in controls (16.94 ± 10 vs. 12.18 ± 7.2 ng/mL; p = 0.004)." (PMID 36674646, 2023). "Post-COVID-19 exhibited lower levels of serum IL-6 (p adj <0.01), whereas it showed higher serum IL-10, triglyceride, leptin, IgG, ACE activity, TNFRSF1A, and PGE2 (p adj <0.05) levels compared with controls." (PMID 37753077, 2023). "In 62 COVID-19 patients whose symptom onset was less than 3 days before hospital admission, circulating leptin levels were elevated in comparison to 62 healthy controls." (PMID 37238973, 2023). "An Important factor that contributes to immune imbalance and worse prognosis in obese COVID-19 patients is chronically increased leptin." (PMID 37240656, 2023). "When compared to healthy subjects, total adiponectin levels were statistically lower in severe COVID-19 while, in contrast, the levels of leptin and resistin were statistically higher." (PMID 36674646, 2023). "The results showed that leptin serum levels were significantly higher in the COVID-19 patients than in healthy controls, with more prominent values in the female population." (PMID 37408184, 2023).